IL6 (interleukin 6)
Diseases named in the same sentence as IL6 in open-access papers (continued):
Sharing a sentence is not in itself a finding about the gene and the disease.
Hypertension (continued). "Our findings expand upon prior research by demonstrating an association between interleukin-6 and MACE in adults with preclinical hypertension and stage 2 hypertension." (PMID 41286084, 2025). "Studies have revealed associations between inflammatory markers, such as CRP, IL-6, and TNF-α with BPV in older hypertensive patients, suggesting a potential mechanistic link between inflammation and target organ damage in hypertension." (PMID 41149270, 2025). "The positive association between hypertension or CVD and GDF15 was mediated 27.9% by TNFR1, 13.6% by IL-6, and 1.9% by TNF-a independently." (PMID 41280118, 2025). "Our findings provide an important starting point for understanding the role of IL-6 in hypertension management." (PMID 39760129, 2025). "Our multivariate analysis identified age, hypertension, NT-proBNP, and IL-6 as independent predictors of APE and in-hospital mortality." (PMID 41303223, 2025). "The cytokine Il6 is increased in many different hypertensive conditions, and a decrease of it has been shown to attenuate hypertension and kidney damage in Dahl SS rats." (PMID 40232853, 2025). "Age, APACHE II score at ICU admission, immunosuppression status, hypertension, IL-6, and APTT measured within 6 h before ECMO initiation were the six predictors included in the nomograms." (PMID 40856884, 2025). "It is postulated that numerous pro-inflammatory markers are elevated in hypertension such as interleukin-17, interleukin-6, interleukin-1β, tumor necrosis factor-α, and inteurleukin-23." (PMID 41003144, 2025). "Reducing IL-6 by genetic knockout attenuated hypertension induced by Ang II infusion and limited renal damage in mice." (PMID 41184958, 2025). "Certainly, IL-6 expression in the hippocampus and hypothalamus enhanced from that at 4 w exposure in mice with hypertension or Pb exposure." (PMID 39853035, 2025). "In genes related to “hypertension,” 3 genes were commonly changing in both male DK and HK groups (Il6, Hmox1 downregulated and Ciart upregulated)." (PMID 40232853, 2025). "We observed IL-6 and TNF-α were also positively related to Clostridium-innocuum-group, which was classified as a risk factor for hypertension, with IL-1R2 (an inflammation-associated receptor) being identified as a significant mediator." (PMID 41154794, 2025). "High IL-6 correlated with Black race, higher BMI, hypertension, and markers of metabolic dysfunction, e.g., elevated HbA1c, C-reactive protein (CRP), and reduced lung function." (PMID 39714726, 2025). "Mice models of hypertension indicated that mineralocorticoid receptor activation facilitates a pro-inflammatory shift, with increased circulating interleukin 6 and MCP-1 levels." (PMID 40721437, 2025). "The positive association between hypertension or CVD and risk of hospitalization or death was mediated 16.4% by TNFR1 and 12.0% by IL-6, as well as 12.4% by GDF15." (PMID 41280118, 2025). "Both ROS and inflammation are central to the development and progression of hypertension, with key roles being played by cytokines like IL-6, macrophages, and T cells." (PMID 40508164, 2025). "Hypertension can activate pro-inflammatory cytokines such as IL-6 and TNF-α, leading to BBB disruption and neuronal damage in conditions such as strokes and TBIs." (PMID 39861166, 2025). "Participants with prevalent PAD, high hsTnT and high NT-proBNP were older, had higher prevalence of hypertension, more were smokers and their concentration of IL-6 was higher." (PMID 40149937, 2025). "Multiple studies have demonstrated that elevated levels of IL-6, ICAM-1, and VCAM-1 are independently associated with incident hypertension, progression of atherosclerosis, and increased cardiovascular events." (PMID 40863231, 2025). "Interleukin-6 and urinary isoprostanes are associated with MACE in adults with preclinical hypertension." (PMID 41286084, 2025).
Hypertension (continued). "In the current study, we demonstrated that elevated IL-6 levels at baseline are associated with long-term AVF failure, independent of age, sex, and cardiovascular risk factors such as DM, hypertension, IHD, and PAD." (PMID 39860495, 2025). "IL-6 contributes to hypertension by activating Janus kinase and signal transducer pathways, increasing sodium channel activity in kidney tubules, and promoting sodium and water retention, particularly in angiotensin II–driven models." (PMID 41149270, 2025). "PWV was significantly related to plasma hsCRP, TNFα, and IL-6 in untreated patients with essential hypertension." (PMID 40943715, 2025). "TCM also reduces the expression of inflammatory factors such as IL-6 and TNF-α, mitigating vascular injury caused by hypertension." (PMID 39717555, 2024). "Immune cells in the brain, including microglia/macrophages, are impacted by hypertension, leading to their activation and expression of pro-inflammatory molecules like IL-1b, IL-6, and TNF-a." (PMID 39144717, 2024). "Individuals with hypertension display elevated levels of pro-inflammatory cytokines, including IL-1β, IL-6, IL-8, IL-17, IL-23, TGF-β, and TNF-α." (PMID 38672199, 2024). "In particular, the American diet results in increased CRP and IL-6 levels in the serum, while Dietary Approaches to Stop Hypertension and Mediterranean diets have decreased inflammatory factor levels." (PMID 39969369, 2024). "According to studies, atorvastatin inhibits the IL-6/STAT3/endothelin-1 pathway in patients with spontaneous hypertension." (PMID 38855751, 2024). "IL-6 treatment increased the expression of epithelial sodium channels in murine kidney cortical collecting duct cells, whereas IL-6 knockout mouse studies have shown that IL-6 is an important mediator of angiotensin II and salt-stimulated hypertension." (PMID 38256155, 2024). "Leptin is primarily secreted by subcutaneous adipose tissue, whereas other inflammatory markers, such as IL-6 are 2-to-3 times higher in visceral adipose tissue when compared to subcutaneous adipose tissue and also contribute to hypertension development." (PMID 37872379, 2024). "According to recent studies, patients with chronic central serous chorioretinopathy who also suffer from hypertension tend to have elevated levels of IL-8 and IL-6 in their plasma." (PMID 38835666, 2024). "Angiotensin II was reported to contribute to the development of hypertension and stimulate IL-6 release from human vascular smooth muscle cells." (PMID 38256155, 2024). "HFpEF patients were observed to have higher circulating IL-6 and IL-8 levels compared to patients with asymptomatic hypertension, and patients with heart failure had higher IL-6 and TNFα levels compared to healthy individuals." (PMID 38256155, 2024). "Elevated proinflammatory cytokines, such as IL‐6 and TNF‐α, have been closely associated with organ damage in both human subjects and animal models of hypertension." (PMID 38504425, 2024). "Heart disease, atherosclerosis, and hypertension are all associated with increased pro-inflammatory cytokines, such as tumor necrosis factor-alpha (TNF-α), interleukin (IL)-1β, IL-6, and interferon-gamma (IFN-γ)." (PMID 37238657, 2023). "Pro-inflammatory cytokine specifically interleukin-6 (IL-6) is elevated in subjects with hypertension." (PMID 37324636, 2023). "Using LASSO binary logistic regression, 19 features were reduced to 9 potential predictors (i.e., Scrpost + PLTpost + CPB > 182 min + D-dimerpost + D-dimerpre + Hypertension + Age > 58 years + IL6 > 18 pg/ml + IL6)." (PMID 37636294, 2023). "Compared with the control group, patients in the hypertension group exhibited higher levels of inflammatory factors including IL-6, IL-8, and TNF-α." (PMID 36851332, 2023). "IL-6 plays an important role in inflammation and can regulate the development of a variety of diseases, including hypertension and other cardiovascular diseases." (PMID 36838830, 2023).
Hypertension (continued). "In our study, we also found that arterial hypertension promoted an increase in Il-6 and TNF-α in bladder tissue." (PMID 36865350, 2023). "Silveira-Nunes found that serum levels of tumor necrosis factor and interleukin-6 increased in patients with hypertension, while the relative abundance of Lactobacteriaceae and Ruminococcaceae decreased significantly." (PMID 37293204, 2023). "The 10 variables with non-zero coefficients in the LASSO logistic regression model (i.e., Scrpost + RBC transfusionU + CPB > 182mi + D-dimerpre + Hypertension + Age > 58 years + Wheats + FET + IL6 > 18 pg/ml + IL6) were used in the final model." (PMID 37636294, 2023). "In our experimental model, Spiro (100 mg/Kg/day) effectively mitigated hypertension, plasma creatinine elevation, and renal overexpression of IL-6 and NGAL in Tac-treated mice." (PMID 37242615, 2023). "Several studies reported that proinflammatory cytokines, such as interleukin-6, play an important role in hypertension and OA." (PMID 37372660, 2023). "IL-6 is enhanced in response to exogenous Ang-II infusion, which increases the activity of the RAS system and ultimately causes hypertension to occur and develop." (PMID 37273529, 2023). "The blood levels of IL-6 in patients with hypertension are higher, and an increase in the levels of IL-6 is related to vasoconstriction and remodeling." (PMID 36838830, 2023). "Increased inflammatory mediators, such as interleukin-6 and tumor necrosis factor, are correlated with the onset of cardiovascular disease in hypertension and osteoporosis." (PMID 37754885, 2023). "Hypertension progression was associated with VEGF-A, IL-6, IL-4, and MCP-3, while newly detected hypertension was linked to IL-9, TNFa, IL12(p40), IFNa2, and EGF." (PMID 37629267, 2023). "An increase in IL-6, IL-17, and ROS levels can promote the occurrence of comorbid hypertension and anxiety." (PMID 37273529, 2023). "We previously found that free radical-mediated lipid peroxidation contributes to IL-6 production in dendritic cells leading to inflammation and hypertension." (PMID 41798717, 2023). "Studies in the genetically modified mouse (IL-6−/− mice) strains have demonstrated that deletion of IL-6 can prevent AngII-induced hypertension." (PMID 37920615, 2023). "HHcy up-regulates the expression of interleukin-6 (IL-6) and nuclear factor-κB (NF-κB) p65/Rela, induces oxidative stress and inflammation, and leads to hypertension." (PMID 36839194, 2023). "Our findings are in agreement with these reports, as serum levels of IL-6, IL-8, IL-10, TNFα were significantly elevated in patients with arterial hypertension." (PMID 37969879, 2023). "On the other hand, HIIT downregulated TNF-α and IL-6 and upregulated IL-10 expression, subsequently attenuating hypertension-induced inflammation." (PMID 36865350, 2023). "Of the six case–control studies, four found elevated postpartum IL-6 levels in pregnancies complicated by hypertensive disorders." (PMID 37887854, 2023). "Whereas, a significant correlation was discovered between the risks of essential hypertension with hypomethylations in the CpG site of IL-6 promoter in which the degree of DNA methylation was diverse among gender." (PMID 37201134, 2023). "Similar patterns of hypomethylation have also been reported for CVD-related conditions, such as Behcet’s syndrome with IL-6 and essential hypertension with IFN." (PMID 38132456, 2023). "Both patients with essential hypertension and hypertensive animal models showed elevated levels of IL-6 in systemic circulation." (PMID 36760555, 2023). "Interleukin-6 (IL-6) plays a critical role in essential hypertension (EH) and cardiovascular disease." (PMID 37920615, 2023). "Clinical and preclinical studies show a correlation between increased levels of IL-6 and cardiovascular changes, for instance, in arterial hypertension." (PMID 36289978, 2022).
Hypertension (continued). "While Il6 expression was unchanged in hypertension or MI, higher Il6 expression was confirmed by real-time PCR in bone marrow endothelial cells from Apoe−/− mice." (PMID 35747128, 2022). "Studies have reported that chemokines (such as TNF-α and IL-6) are involved in the formation of hypertension." (PMID 35668772, 2022). "Mounting evidence indicates that IL-6 has a crucial role in aspects of the chronic inflammatory response, such as hypertension, rheumatoid arthritis, and ischemic heart disease." (PMID 36703963, 2022). "Inflammation is one of the several pathogeneses of hypertension, and inflammatory factors such as IL-6 are involved in the development and progression of hypertension." (PMID 35345408, 2022). "Case 1 had lymphopenia, elevated IL-6 and history of hypertension, while case 2 had leukocytosis and an increased liver enzymes." (PMID 35044234, 2022). "The indicators of pro-inflammatory status (C-reactive protein, TNF-α, IL-6), corresponding to the normative range of values, were higher in males than in females both in uncomplicated hypertension and in the presence of HFpEF." (PMID 35997392, 2022). "After adjusting expectoration, chest pain, low fever, COPD, IFN-γ, hypertension, hemoptysis, IL-4, IL-6, and IL-12, miR-378 was independently correlated with the activity of TB patients (P = 0.047, OR = 39.016, 95% CI: 1.054–1444.199)." (PMID 35305574, 2022). "We give specific introduction to recent findings of MCP-1, IL-6, TNF-β and IL-10 in hypertension and show underlying effect in the pathogenesis of effects on kidney, cardiovascular and other tissues." (PMID 36195874, 2022). "Olmesartan also reversed left ventricular hypertrophy in rats with restorative hypertension by lowering IL-6 levels." (PMID 35163696, 2022). "Hypertension is a known risk factor for fibrosis, and increased plasma IL-6 levels, mediated by Ang II, tend to correspond with increased systolic blood pressure and decreased endothelial function, indicating that IL-6 may play a role in increasing blood pressure and decreasing cardiac function." (PMID 35455995, 2022). "Arterial hypertension (AH) associated with low EAT and PVAT ADIPOQ, and high EAT LEP, SAT, as well as PVAT LEPR, and IL6 in SAT and EAT." (PMID 36157437, 2022). "In fact, apart from the direct promoting effect on hypertension, IL-6 is also reported to induce the differentiation of immature T cells into Th17 cells and is involved in the process of hypertension." (PMID 36195874, 2022). "The study has demonstrated that IL6 and TNF, as inflammatory factors, are independent risk factors for hypertension." (PMID 35360657, 2022). "AT II plays an important role in the development of hypertension-induced cardiac fibrosis by stimulating the production of IL-6 and TGF-β1 in cardiac fibroblasts." (PMID 36009511, 2022). "Experiments showed that the AngII induced hypertension was relieved in the IL-6−/− mice, suggesting a key role IL-6 plays in the induction of hypertension depending on JAK2/STAT3 pathway in the kidney." (PMID 36195874, 2022). "Melatonin also decreased hypertension, placental IL-6 expression, oxidative stress and proteinuria in murine models of PE." (PMID 35453333, 2022). "First, via network pharmacology, IL-6 is identified as one of the key targets of HQQR against early renal damage in hypertension, and inhibition of inflammation is a crucial process." (PMID 35668772, 2022). "In conclusion, this study demonstrated that stimulated IL-6 production in activated macrophages contributes to intrarenal AGT augmentation in the early stages of Ang II-dependent hypertension, which leads to the development of kidney injury." (PMID 35887028, 2022). "IL6 can influence the development of Ang II-mediated hypertension by intervening the JAK2/JAK3 pathway." (PMID 35360657, 2022).
Hypertension (continued). "The nuclear receptor NR1D2 promotes expression of the inflammatory mediator, interleukin 6, a pathway that has been described to be involved in trophoblast hypoxia, arterial hypertension, placental inflammation, and autophagy in gestational diabetes mellitus." (PMID 36284122, 2022). "IL-1β is an “early-response” cytokine which is produced by macrophages and monocytes, promotes the release of IL-6 as consequence of oxidative stress, a cardinal process in the pathogenesis of hypertension." (PMID 36247461, 2022). "Compared to females, males with essential hypertension complicated by HFpEF display significantly higher blood levels of pro-inflammatory autacoids: C-reactive protein, tumor necrosis factor alpha, and interleukin-6." (PMID 35997392, 2022). "IL-6, TNF-α, and CRP can cause vascular endothelial dysfunction and participate in the occurrence of hypertension during pregnancy." (PMID 34790247, 2021). "Together these findings suggest that HHcy promotes an inflammatory status and can synergistically aggravate the arterial damage of hypertension, at least in part, through the NF-κB p65/Rela/IL-6 molecular pathway." (PMID 34603014, 2021). "Compared with the hypertension group, the hypertension combined with HHcy group up-regulated the expression levels of interleukin-6 (IL-6) and nuclear factor-κ-gene binding (NF-κB) p65/Rela, but not NADPH oxidase (Nox)." (PMID 34603014, 2021). "The results of our study confirmed positive correlations between systemic hypertension and plasma IL‐8, IL‐6 and TNF‐α levels in chronic CSC." (PMID 32701204, 2021). "The associations of hypertension and HDL-C with physiological successful aging over six years stratified by important variables (baseline age, CRP, and IL-6)." (PMID 34847175, 2021). "Compared with obese IL-6-low asthmatics, the obese IL-6-high asthmatic group had strong signals for metabolic dysfunction, such as history of hypertension, and increases in total blood leukocytes and blood neutrophils." (PMID 33418879, 2021). "The increased expression of C-reactive protein (CRP) and interleukin-6 (IL-6), two important circulating markers of inflammation, were found after sleep deprivation, and has been shown to predict cardiovascular events, hypertension and type two diabetes." (PMID 33479186, 2021). "Previous study showed an association of baPWV and augmentation index with inflammatory markers, such as CRP, tumor necrosis factor-alpha (TNF-α) and Interleukin-6 (IL-6) in hypertension patients and CRP in healthy individuals." (PMID 34330221, 2021). "Only after cooperating with hypertension, HHcy increased the expression levels of IL-6 and NF-κBp65/Rela." (PMID 34603014, 2021). "For instance, in the Dahl salt-sensitive rat model of hypertension, sGC stimulators decreased the levels of plasma interleukin 6 (IL-6)." (PMID 34537066, 2021). "In particular, patients with hypertension and cardiovascular and cerebrovascular diseases had more serious inflammatory conditions, as indicated by higher levels of IL-6." (PMID 34123873, 2021). "Hypertension is associated with an increase in blood levels of pro-inflammatory cytokines such as TNF, IL-6, monocyte chemoattractant protein-1(MCP-1), and sICAM-1 which can contribute to BBB disruption." (PMID 34054705, 2021). "Recent studies have demonstrated that treatment with Nuruk extract is associated with a decrease in LPS-induced nitrite and IL-6 levels in RAW 264.7 cells, and also has an inhibitory effect on hypertension, migration, platelet aggregation, and angiogenesis." (PMID 34836159, 2021). "Single-factor logistic regression analysis showed that BMI, a history of hypertension, FPG, HbA1c, and the serum TC, IL-6, and IL-10 concentrations were risk factors; whereas, the serum Zn and Mg concentrations and eGFR were protective." (PMID 33859989, 2021). "Inhibition or genetic deletion of IL-6 prevented the detrimental effects of angiotensin II, including hypertension, ET-1 expression, and renal injury/fibrosis." (PMID 33668632, 2021).